TNF (tumor necrosis factor)
Diseases named in the same sentence as TNF in open-access papers (continued):
Sharing a sentence is not in itself a finding about the gene and the disease.
Obesity (continued). "As the level of inflammation increases, the state of obesity and therefore percentage body fat also progresses; thus, we evaluated the relationship between the gene expression levels of IL6 and TNFα against the percentage body fat of chow (C)- and high-fat (HF)-fed mice in gWAT, iWAT, iBAT and PAT." (PMID 32580292, 2020). "Besides, mice with 10 days of life showed diminished WAT adipogenic capacity, as well as increased hepatic steatosis, indicating that TNF-α signaling pathway is essential for WAT expansion and remodeling during obesity." (PMID 33117273, 2020). "It has been reported that circulating tumor necrosis factor-alpha (TNF-α) concentration and its mRNA expression are higher in patients with obesity and IHD (37 subjects) in comparison with patients without cardiovascular disorders (20 subjects)." (PMID 32121175, 2020). "There is evidence that the release of proinflammatory cytokines, such as Tumor Necrosis Factor α (TNFα) and Monocyte chemoattractant protein 1 (MCP-1) that can occur in obesity is driven by stress responses related to WAT expansion, although specific mechanisms involved remain to be elucidated." (PMID 33854494, 2020). "In light of the key role of iRhom2 in TACE-mediated proteolytic shedding of TNF-α, we hypothesized whether 4-HIL could modulate iRhom2 to reverse obesity-induced inflammation." (PMID 33298044, 2020). "Tumor necrosis factor (TNF), which is mostly expressed and secreted by adipose tissue macrophages, was one of the first cytokines shown to be increased in adipose tissue and circulation of people with T2D and obesity." (PMID 33178196, 2020). "In the obesity-cancer relationship, multiple biological processes including insulin, insulin-like growth factor (IGF)-1, insulin resistance, sexual hormones (estrogens) and pro-inflammatory cytokines (TNF-α, IL-6 and CRP) actively participate." (PMID 32811441, 2020). "Serum levels of TNF-α were higher in obese children than in healthy subjects and they were not correlated with central and global obesity." (PMID 33202729, 2020). "Obesity releases free fatty acids (FFA) that trigger the Toll-like receptor 4 (TLR4) signaling pathway, resulting in the activation of the nuclear factor-kappaB (NF-κB), a master transcription regulator in the production of pro-inflammatory cytokines, TNF-α." (PMID 32751794, 2020). "Moreover, the secretion of proinflammatory cytokines like TNF-α, IL-6, and MCP-1 promotes JNK, IKK-β/NF-κB, and inducible iNOS pathways, further enhancing the inflammatory process induced by obesity, facilitating the development of insulin resistance." (PMID 32806722, 2020). "Many studies have shown that KD approaches had an anti-inflammatory effect by reducing inflammatory markers, including C-reactive protein, TNF-α, MCP-1, interleukin-6 (IL-6), and IL-8, which are generally higher in obesity." (PMID 32848830, 2020). "The effect of burns and obesity on the relative expression of MCP-1, TNF-α and IL-1 β protein." (PMID 33354433, 2020). "Increases in IL-1β and TNFα, have been proposed to contribute to the innate AHR of obesity." (PMID 32326950, 2020). "Furthermore, elevated levels of MIP-1α/CCL3 positively correlate with TNF-α and CD163 in fat tissues from individuals with obesity." (PMID 33050324, 2020). "Furthermore, it has been demonstrated that metformin diminishes TNFα and MCP1 production in adipose tissue in a rodent obesity model with insulin resistance." (PMID 32967076, 2020). "Though obesity is not an issue in our study, due to small sample size, TNF-α and IL-12 demonstrated only a nonsignificant decrease after T&A." (PMID 32260590, 2020). "An involvement of TNFα and IL-1β in the activation of YAP and TAZ in mouse adipocytes during obesity could be demonstrated by treating animals with the TNFα inhibitor etanercept and the IL-1β inhibitor anakinra." (PMID 33116140, 2020).
Obesity (continued). "Similar to obesity, aged ATMs display an elevated expression of the chemokine receptor CCR2, possessed enhance secretion of pro-inflammatory cytokines IL-6, MCP-1, and TNFα, and a decrease in expression of PPARγ, which mechanistically accounts for the loss in M2 ATMs." (PMID 32499756, 2020). "The top differentially expressed genes affected by upstream transcriptional regulators IFNγ, LPS, and TNFα displayed an overlap in HFD and ARE-Del-/- mice, indicating that obesity-induced liver inflammation may be dependent on signaling via IFNγ." (PMID 33379198, 2020). "Indeed, co-administration of Fat1562 with anti-TNFα led to a striking increase of VAT-Treg cells and a significant improvement in insulin sensitivity in mice with severe obesity." (PMID 32773038, 2020). "Nowadays, almost 30 years later, the link between obesity, diabetes and chronic inflammation has been confirmed and it has been also proved that mice lacking functional TNF-α are more insulin sensitive and glucose tolerant than wild type animals." (PMID 33114564, 2020). "Factorial analysis showed that obesity and burn severity had no interactive effect on TNF-α expression." (PMID 33354433, 2020). "Research about the role of TNF-alpha in obesity and diabetes is not settled yet and is still a subject of active research work." (PMID 32089876, 2020). "The effect of burns and obesity on the expression of MCP-1, TNF-α and IL-1β protein." (PMID 33354433, 2020). "For instance, TNF-α expression in macrophages was greater in cord blood samples from neonates born of mothers with obesity than that in those born of mother without obesity." (PMID 32911676, 2020). "Although obesity is considered a low-grade systemic inflammatory state, in the present study, we did not observe differences in us-CRP and in most of the cytokines analysed in blood serum (IL-6, TNF-α, IL-1β, IL-10, MCP-1 and leptin)." (PMID 33489104, 2020). "Thus, all animals with obesity were expected to show high concentrations of both TNF-α plasma concentrations, TNF-α gene expression and immunostaining for TNF-α positive in the analyzed adipose tissue." (PMID 30818882, 2019). "Increased circulatory levels of TNF-α, palmitate and CCL4 are co-expressed in obesity." (PMID 31546972, 2019). "Additionally, the excessive fat in obesity, especially visceral fat, produces cytokines including MCP-1, IL-6, and TNF-α, and adipokines such as leptin, which regulate pro-inflammatory cytokines." (PMID 31123488, 2019). "Obesity induced by high-fat diet (HFD) is accompanied by not only the body weight increase, adipose deposition in liver and other organs, but also oxidative stress and inflammation increase, such as IL-1β, TNF-α and iNOS." (PMID 30736329, 2019). "In our JIA population, obesity/overweight corresponds to a worse trend in the therapeutic response both to first-line treatments and to anti-TNF drugs, although without reaching statistical significance." (PMID 31249526, 2019). "In the patients without T2DM (with grade I and II obesity), the relative expression levels of TNF-α and RARRES2 genes in the GO were correlated." (PMID 30871547, 2019). "High secretion of tumor necrosis factor-alpha (TNF-α), interleukin-6 (IL-6), monocyte chemoattractant protein-1 (MCP-1), and additional products of macrophages by adipose tissue with low sensitivity to insulin has also been detected in obesity." (PMID 30678306, 2019). "This study focused on adolescents aimed to investigate early changes in obesity-related cardiac dysfunction, and to explore the correlations between indices of cardiac dysfunction and serum biomarkers, including hs-CRP, TNF-α, interleukin-6, M30 monoclonal antibody, and insulin resistance." (PMID 31120986, 2019). "The cumulative evidence from such studies indicates that circulating TNF-α levels are inconsistently elevated in either adult patients with OSA independent of obesity or in children." (PMID 30678164, 2019).
Obesity (continued). "A marginal association was found between rs925946 in LGR4-LIN7C-BDNF and rs1800750 in TNF-α with obesity but does not reach statistical significance." (PMID 31354816, 2019). "In contrast, peritoneal macrophages displayed TNF-α/IL-10 ratios that were intermediary to AT-SVF and alveolar macrophages, and, unexpectedly, assumed a less pro-inflammatory cytokine response to LPS in obesity." (PMID 31316525, 2019). "Finally, TCRδ knockout mice had less CD11c+CD206− M1-like and TNF-α+-macrophage infiltration in epiWAT in response to HFD, suggesting multiple direct and indirect functions of γδ T cells in obesity." (PMID 31379820, 2019). "AT macrophages (ATM), which can account for up to 50% of the cellular content in the obese AT, are the primary source of pro-inflammatory cytokines (e.g., IL-6, TNF-α, IL1-β), and have been shown to be centrally important in obesity-related metabolic dysfunction." (PMID 31277269, 2019). "TNFα plays a key role in obesity-related insulin resistance, and increased TNFα levels contribute to impaired glucose homeostasis; however, the role of TNFα as an adipokine in the IH condition has not been fully elucidated." (PMID 31013606, 2019). "Studies have shown higher levels of TNF-α and higher expression of TNF-α mRNA in the tissues of obese, insulin-resistant patients with T2D, as well as in the adipose tissues of several rodent models of obesity and T2D." (PMID 31635166, 2019). "It has been reported that TNFα concentration in adipose tissue is correlated with obesity and insulin resistance in patients with and without type 2 diabetes." (PMID 30658634, 2019). "In the WAT, the obesity-induced chronic low-grade inflammation leads to the production and release of cytokines, such as monocyte chemoattractant protein-1 (MCP-1), interleukin-6 (IL-6) and tumor necrosis factor α (TNF-α)." (PMID 31426291, 2019). "In the present study, we determined the associations of AGE markers such as dietary CML (dCML) with body mass index (BMI) and waist circumference (WC) as obesity and central obesity parameters, respectively, through the plasma CML (pCML), and plasma TNF-α (pTNF-α) parameters, in Indonesian women." (PMID 31847322, 2019). "Studies have also shown that there is an increased inflammatory response related with the presence of hyperleptinemia without obesity, and that leptin is able to control TNF-α production and activation by macrophages." (PMID 29189992, 2018). "Since both obesity and T2DM are pro-inflammatory states, we examined the expression of several M1 phenotype markers in PBMC of lean, obese, T2DM, and T2DM on Metformin, including CD86, CD11c, CD169, IL-6, TNFα, iNOS, and CD36." (PMID 30356719, 2018). "In addition to genetic variations, environmental stimuli of inflammatory processes, such as smoking and obesity, were shown to influence TNF-α protein concentrations, further contributing to individualized differences in TNF-α level." (PMID 29849987, 2018). "Secretion of TNF-α reduces the secretion of adiponectin from adipocytes, consistent with increased inflammation in the white adipose tissue during the onset of obesity reducing the secretion of chemerin in white, but not brown, adipose tissue." (PMID 30161155, 2018). "Tumor necrosis factor alpha (TNF-α) is a well-known inflammatory marker produced by the macrophages of the stromal vascular tissue from the adipose tissue and has increased circulating levels in obesity-inducing insulin resistance." (PMID 29849863, 2018). "Obesity is a metabolic disease characterized by low grade chronic inflammation, usually accompanied by dyslipidemia and up-regulation of other bioactive molecules such as CRP and TNF-α." (PMID 30572569, 2018). "Evidence shows that obesity results in chronic low-grade inflammation, which may elevate CRP levels due to the adipose tissues releasing IL-6 and TNF-α and inducing the synthesis of CRP by the liver." (PMID 30065944, 2018).
Obesity (continued). "Obesity, impaired IS or T2DM are characterized by low-grade inflammation frequently assessed by CRP as well as interleukin 6 (IL-6) or tumor necrosis factor alpha (TNFα)." (PMID 30294302, 2018). "In obesity, inflammation can occur due to increased levels of chemokines (such as CCL2 and CXCL1) and inflammatory cytokines (such as tumor necrosis factor α (TNF-α) and interleukin-6 (IL-6)) secreted from accumulated fat in hepatocytes and adipocytes, causing insulin resistance." (PMID 29967759, 2018). "In addition, in a diet-induced obesity (DIO) mouse model, mice orally challenged with P. gingivalis presented with reduced levels of inflammatory mediators TNF-α, IL-6, and serum amyloid A (SAA)." (PMID 29621153, 2018). "Further understanding of the NF‐κB, TNF‐α, and CCR2 pathways could lead to effective interventions for obesity‐induced CKD." (PMID 29632818, 2018). "Our findings of negative impact of obesity on treatment response to anti-TNF agents suggests that obesity is a negative prognostic factor and treatment effect modifier that must be considered in clinical trial design and clinical practice." (PMID 29771924, 2018). "The first study that established the reframing of obesity as an inflammatory condition demonstrated the detrimental effect of tumor necrosis factor alpha (TNF-α), an inflammatory mediator secreted by adipose tissues, on insulin resistance in many animal models of obesity." (PMID 29951059, 2018). "More than two decades ago, Hotamisligil and colleagues discovered the negative impact of tumor necrosis factor α (TNFα) on insulin sensitivity in obesity." (PMID 30591653, 2018). "A key event in obesity is characterized by macrophage infiltration in adipose tissue, which triggers increased secretion of pro-inflammatory adipokines such as monocyte chemoattractant protein-1 (MCP-1) and tumor necrosis factor α (TNFα)." (PMID 29018280, 2017). "On the one hand, TNFα knockout mice exhibit normal glucose tolerance when exposed to normal food, but are protected from the development of obesity-induced insulin resistance in the absence of body weight gain alterations on the other." (PMID 28233125, 2017). "Fourth, the impact of obesity on the relationship between circulating TNF-alpha and OSAS cannot be solved due to the lack of necessary data, although it is increasingly recognized that obesity is an established risk factor for OSAS." (PMID 28187003, 2017). "As adipose tissue inflammation is a key feature of obesity and insulin resistance, we hypothesised that SIK expression is regulated by the inflammatory cytokine TNF-α." (PMID 27807598, 2017). "In obesity, the enlarged adipose tissue is infiltrated by a large number of macrophages, due to which production of pro-inflammatory adipokines such as MCP-1, IL-6, and TNFα increases." (PMID 28248545, 2017). "A study showed that CCDC3 could repress TNF-α/NF-KB-induced a pro-inflammatory response in endothelial cells, suggesting a potential role for CCDC3 in the development of obesity and atherosclerosis." (PMID 28827783, 2017). "In this study, we used 4-1BB-deficient obese mice fed an HFD to investigate whether the 4-1BBL and 4-1BB system, another member of the TNF-TNFR superfamily, participates in obesity-induced skeletal muscle atrophy." (PMID 28503098, 2017). "Collectively, deciphering organ-specific downstream actions of TNFα in obesity-induced insulin resistance revealed redundant as well as non-redundant kinase functions on inhibitory IRS serine phosphorylation." (PMID 28233125, 2017). "In obesity, BAT cell apoptosis is increased due to the decrease in Bcl2 and increase in TNF-α; however, low temperature can upregulate the Bcl2 gene expression and may protect BAT against apoptosis in cold situations." (PMID 28607631, 2017). "In the context of obesity, where TNF-α is chronically elevated, TNF-α may play a pro-carcinogenic effect." (PMID 28402277, 2017).
Obesity (continued). "It was observed that deletion of CERK suppressed high-fat diet obesity-mediated inflammatory cytokines IL-6 and TNFα and showed normal insulin signaling in an animal model." (PMID 29269995, 2017). "In contrast, obesity induces lipolysis and release of pro-inflammatory free fatty acids (FFAs) and factors such as C–C motif ligand 2 (CCL2) and TNF-α that recruit blood monocytes in adipose tissue, where they become polarized to the highly pro-inflammatory M1-like state." (PMID 28018292, 2016). "Within liver tissue, hepatic transcript levels of Tnf-α were persistently upregulated in obesity and HCC, but this did not translate into increased expression of hepatic TNF-α." (PMID 30873458, 2016). "The proinflammatory cytokines TNF-α and IL-18 are known to be elevated in obesity/T2D while IL-8 or CXC chemokine ligand (CXCL)-8 is an inflammatory protein and increased circulatory numbers of IL8-expressing monocytes were also reported in human obesity." (PMID 27980459, 2016). "Recently, the obesity has been considered a physiological state of chronic inflammation, characterized by elevated levels of inflammatory markers including C-reactive protein (CRP), interleukin-6 (IL-6), and tumor necrosis factor alpha (TNF-α)." (PMID 27899895, 2016). "Interaction effects between dietary FAs and variations in inflammation-related genes such as tumor necrosis factor α (TNF-α) and interleukin 6 (IL6) may influence obesity phenotypes." (PMID 26999109, 2016). "However, when obesity was induced with a high‐fat diet, CTRP3 transgenic mice had lower circulating levels of IL‐5, TNF‐α, sVEGF2, and sVEGFR3, and a higher level of soluble gp130." (PMID 26997632, 2016). "The metformin treatment (only at the higher concentration) resulted in a decrease in the TNFα production to comparable levels in blood cultures derived from all NAFLD patients—regardless of the presence of obesity (P≤0.01)." (PMID 26930651, 2016). "foz/foz mice developed obesity, hyperinsulinemia, diabetes, adipokine dysregulation and fatty liver, without increased serum or liver TNF-α or serum IL-6." (PMID 30873458, 2016). "TNF-α, a key proinflammatory cytokine, positively regulates PTP1B expression in adipocyte, hepatocyte cell lines, and mouse hypothalamus as well as in an animal model of high-fat diet-mediated obesity." (PMID 27095436, 2016). "Neutralization of TNF improves glucose uptake in murine obesity and mice lacking TNF are protected from high-fat-diet-induced insulin resistance." (PMID 27148273, 2016). "The relationship of clinical severity and osteopontin was higher when not controlled by anthropometric measures, but it was attenuated when not controlled by TNF-α, indicating a possible common pathway between obesity and osteopontin." (PMID 27629533, 2016). "Adipocytes and infiltrating inflammatory cells (primarily macrophages) present within the tissue secrete key inflammatory proteins, such as TNF-a, IL-6, and CCL2/monocyte chemoattractant protein, and their gene expression and release are markedly increased in obesity." (PMID 25887648, 2015). "The absence of TNF-α results in significantly improved insulin sensitivity in both diet-induced and ob/ob model of obesity." (PMID 26339623, 2015). "Obesity may not be only associated with lung mechanics, such as airway closure during tidal breathing and reduced expiratory residual capacity, but also with a high expression of certain inflammatory mediators, such as tumor necrosis factor (TNF)-α, interleukin (IL)-6, and leptin." (PMID 25658739, 2015). "Specifically in this setting, IL-6 has biological roles including induction of lipolysis and suppression of TNF production, in contrast to the negative effects of IL-6 in obesity and adipose tissue." (PMID 26549941, 2015). "Noteworthy, the major source of TNF-α as well as of multiple cytokines and chemokines in obesity are phagocytes, not adipocytes." (PMID 26090072, 2015).